ENSG00000287636 (novel transcript, antisense to C7orf33 and CNTNAP2)
Synonyms: LOC124901766
Gene: Long non-coding RNA gene on chromosome 7 (148,343,367 to 148,627,654, reverse strand). Ensembl gene ENSG00000287636.
Gene Ontology:
Biological process: RNA processing
Cellular component: nucleolus